GRHL2 (grainyhead like transcription factor 2)
Diseases named in the same sentence as GRHL2 in open-access papers (continued):
Sharing a sentence is not in itself a finding about the gene and the disease.
tumor (continued). "It is generally assumed that GRHL2 activity may be dependent on the tumor type and/or stage of disease progression by regulating distinct target genes in diverse cancer types." (PMID 40889682, 2025). "Despite overwhelming evidence for both tumor-suppressive and protumorigenic roles of the GRHL2 transcription factor in a large variety of human tumors, mechanisms modulating expression or activity of GRHL2 in cancer cells still are largely unknown." (PMID 40889682, 2025). "Our study demonstrates that GRHL2 levels can contribute to modulation of adenosine production by tumor cells, but further (in vivo) work is required to reveal the relative contribution of adenosine produced by GRHL2-negative tumor cells in such a complex environment." (PMID 38706844, 2024). "A key mechanism by which GRHL2 may suppress aspects of tumor progression is through inhibition of epithelial-to-mesenchymal transition (EMT)." (PMID 36691073, 2023). "The roles of GRHL2 may be tumor type- and stage-specific through regulating different target genes in different cancers." (PMID 36691073, 2023). "GRHL2 acts as a tumor suppressor in this type of cancer, where it inhibits EMT by targeting ZEB1." (PMID 35269877, 2022). "Taken together, these data suggest that specific CREs were reprogrammed by the master regulator’s shift from ER to GRHL2 within a single luminal tumor, which led to the establishment of tumor subpopulations with potential for intrinsic endocrine resistance and ultimately poor outcomes." (PMID 35676392, 2022). "Tumor-derived extracellular vesicles containing miR-1290 via Grhl2/ZEB1/PD-L1 axis could promote the immune escape of cancer cells." (PMID 36405753, 2022). "GRHL2 enhances the effect of carcinogenesis and promotes tumour cell proliferation." (PMID 35090432, 2022). "Indeed, GRHL2 has been identified as the FOXA1 interaction partner at the ER bound-active enhancer regions demarcated with H3K4me1/me2 marks to promote tumor progression." (PMID 32974388, 2020). "Within these, alteration in ATP1A1 may pre-dispose to well-differentiated tumours, whereas alterations in GRHL2 may pre-dispose to more poorly differentiated and potentially poorer prognosis tumours." (PMID 30202019, 2018). "Alternatively, JNK may elicit tumor-suppressive effects, as does GRHL2 in certain pathological context, in part depending on the state of cancer progression." (PMID 29735981, 2018). "Hence, the elevated TGF-β signaling in the tongue tissues of the Grhl2 KO mice would pose strong tumor-suppressive effects, impeding the carcinogenic events induced by 4-NQO." (PMID 29735981, 2018). "Additionally, liver metastatic cells compared to pair‐matched primary tumor cells show a significant increase in relative GRHL2 expression." (PMID 28960866, 2017). "Hence, the role of GRHL2 as a tumour suppressor in EOC can only be surmised from the positive correlation of GRHL2 expression with a better survival." (PMID 26887977, 2016). "The role of GRHL2 in regulating tumour growth requires further clarification." (PMID 26887977, 2016). "In addition, GRHL2-high tumours showed better overall survival (OS) in patients as compared with GRHL2-low tumours (Hazard Ratio = 1.578; p = 0.0168)." (PMID 26887977, 2016). "Although yet to be directly experimentally tested, these predictions are congruent with recent reports demonstrating that overexpression of GRHL2 can promote tumor growth and metastasis in vivo, and offer a possible explanation for downregulation of GRHL2 suppressing tumor growth in vivo." (PMID 27008704, 2016). "Perhaps GRHL2 plays an important role in tumor development in many cancer types." (PMID 25994056, 2015). "Interestingly, higher GRHL2 expression is significantly correlated with two unfavorable prognostic characters - progressive tumor grade III and large tumor size (>2 cm) at the time of diagnosis." (PMID 23441166, 2013).
tumor (continued). "We thus theorize that, in the context of the molecular function of the gene(s) critical for tumor progression, such as GRHL2, creating an individualized profile of a patient is the key for translating cancer biology and informatics observations into clinical utility." (PMID 23441166, 2013). "Next, we tested whether Grhl2 mediated promotion of tumor growth and metastasis is through its regulated genes." (PMID 23284647, 2012). "In mouse models, over-expression of Grhl2 significantly promotes tumor growth and metastasis." (PMID 23284647, 2012). "Given the essential role of Grhl2 in determining the epithelial phenotype, Grhl2 could play a pivotal role at the final step of tumor metastasis, and this possibility will require further studies." (PMID 23284647, 2012). "The tumor microenvironment may modulate GRHL2 and E-cadherin expression in drug-resistant cells." (PMID 39897079, 2024). "Hence, elevated levels of GRHL2 could support ER-positive breast cancer progression by supporting plastic, resilient tumor-initiating cells." (PMID 39199676, 2024). "Additionally, as a well-known tumor suppressor, miR-217 targeted Grainyhead-like 2 (GRHL2), a developmental transcriptional factor with ability of influencing epithelial barrier function and keratinocyte differentiation, to inhibit keratinocyte proliferation and promote cell differentiation." (PMID 35075118, 2022). "To verify this previously unknown cell-of-origin for pRCC, we recruited an independent pRCC cohort of 50 patients from Drum Tower hospital and performed immunofluorescence staining with the PT marker AQP1, the CD_PC marker GATA3 or GRHL2, on tumor samples from these patients." (PMID 35013217, 2022). "Hence, aberrant GRHL2 overexpression in OSCCs may abrogate the TGF-β-mediated tumor-suppressive effects through these biochemical effects of MAP kinases." (PMID 29735981, 2018). "Interestingly, the genes CDH1, ESRP1 and GRHL2 have been shown to play critical roles in epithelial-mesenchymal transition (EMT), a process associated with metastatic events in cancer and also highly relevant to tumor progression." (PMID 23887935, 2013). "The analyses identify 3,447 tumor‐specific oncogenic enhancers (SOEs) enriched for master transcription factors (SOX2, TP63, KLF5, GRHL2) that orchestrate malignant programs." (PMID 40899632, 2025). "Several tumor-specific TFs were detected within the ED and SED, including TP63, FOSL1, JUND, GRHL2, SNAI2, KLF5, TP73, and SMAD3." (PMID 41323280, 2025). "Some TFs were specific for individual cell lines, others were shared between two cell lines, and a total of eight TFs were shared amongst all three tumor types, including TEAD1, TEAD2, TEAD3, TEAD4, GRHL2, RUNX2, AP1, and GATA6." (PMID 38912065, 2024). "However, GRHL2 has not been previously implicated in the interaction of tumor cells with T cells." (PMID 38706844, 2024). "We therefore examined how GRHL2 deletion, by increasing CD73 expression and adenosine production, affected recruitment of CD8+ T cells to tumor cells using the MCF-7 conditional KO model." (PMID 38706844, 2024). "It has been revealed that GRHL2, a transcription factor located in 8q22, shows frequently high levels expression in HCC tissues and promotes tumor growth in HCC." (PMID 38862581, 2024). "Given the emerging link between mesenchymal properties and GBM tumor cell survival during therapy (resistance) or following therapy (recurrence), we tested whether the observed change in mesenchymal proteins with GRHL2 alone was sufficient to trigger detectable levels of apoptosis." (PMID 37761927, 2023). "GRHL2 affects cell morphogenesis and epithelial–mesenchymal transition (EMT) and acts as a tumor suppressor in various tumors." (PMID 32326232, 2020). "The tumor promoting factors MUC16, MACC1 and GRHL2 were downregulated in PitNETs after SSA/DA therapy and in GH3 cell following octreotide treatment." (PMID 33680922, 2020).
tumor (continued). "Three tumor development promoting factors MUC16, MACC1, and GRHL2, were significantly downregulated in therapy administered PitNET tissue; this finding was supported by functional studies in GH3 cells." (PMID 33680922, 2020). "Next, we compared accessibilities in subsamples with different tumor fractions for TFs selected based on our previous ATAC-seq and nucleosome plasma mapping, i.e., GRHL2, EVX2, DLX2, HNF4A, LYL1, and PU.1." (PMID 31604930, 2019). "We observed already statistically significant different accessibilities between healthy controls and COAD samples for TFs HNF4A and DLX2 and the other TFs, GRHL2, EVX2, LYL1, and PU.1 showed statistically significant differences at a 1% tumor level." (PMID 31604930, 2019). "GRHL2, whose binding motif is similar to that of GRHL1, functioned as a tumour suppressor, and its expression reduces invasion and migration in GC50." (PMID 28801683, 2017). "To better understand this issue, we investigated the effects of Grhl2 on TGFβ-induced EMT, which was closely related to tumor metastasis." (PMID 28067907, 2017). "Taken together, the tumor proliferation marker MKI67 and a new prognosis marker GRHL2 collaborate with several mesenchymal markers as a “poor-prognosis” gene-set, while two epithelial markers perform as a “good-prognosis” gene-set." (PMID 23441166, 2013). "GRHL2-positive tumors or tumor areas were mostly CD73 negative; GRHL2-negative tumors or tumor areas showed a mixed pattern for CD73." (PMID 38706844, 2024). "For a tumor-specific TF, GRHL2, we observed a negative correlation between the central coverage and tumor fraction, as expected (Pearson’s r = −0.62)." (PMID 36463275, 2022). "When the expression of GRHL2 was silenced in RC-124 non-tumorigenic kidney cell line, this increased cell proliferation and reduced apoptosis, further supporting the tumor suppressive role of GRHL2." (PMID 35269877, 2022). "We hypothesize that GRHL2, a MET inducer, activates CD133 to promote CTC stemness and to allow CTCs to settle and grow in a new distant organ where they will form a secondary tumor." (PMID 34771571, 2021). "Secondly, GRHL2 suppresses TGF-β mediated migratory and invasive capabilities of gastric, breast, and oral cancer cells, where the activation of TGF-β signaling cascade is a significant inducer of EMT in tumor progression." (PMID 32974388, 2020). "Chronic oral exposure to 4-NQO led to strong nuclear staining for GRHL2 in Grhl2 WT tumor revealed by immunohistochemistry (IHC), while the tongue epithelium apparently lacked such staining in Grhl2 KO mice administered with Tmx at all time points." (PMID 29735981, 2018). "Multivariate Cox proportional hazards analysis of these five significant DMFS factors indicated independence between GRHL2 expression and the other three clinical characters but not the histological grade of the tumor." (PMID 23441166, 2013). "Our data have shown that Grhl2 and Wnt7A1 promote epithelial gene expression and tumor progression while Wnt7A2 promotes EMT but inhibits tumor progression, suggesting that 4T1 tumor progression in vivo might be associated with the epithelial phenotype." (PMID 23284647, 2012).
cancer (67 papers, 2012 to 2026). A tumor composed of atypical neoplastic, often pleomorphic cells that invade other tissues. "As user-defined regions of interest, we selected 10,000 binding sites of LYL1, a transcription factor (TF) associated with hematopoietic cells, and GRHL2, an important pioneer TF for epithelial cells playing a role in a wide variety of cancer types." (PMID 39704700, 2024). "An EMT response to GRHL2 loss is limited and our findings indicate that regulation of epithelial genes can be strikingly different in normal and cancer cells involving direct GRHL2-mediated transcriptional control or indirect mechanisms." (PMID 36691073, 2023). "The function of GRHL2 likely is context-dependent and the consequence of GRHL2 loss depends on the cancer type and the stage of cancer progression." (PMID 36768838, 2023). "GRHL2 has been implicated in many cancers such as breast, lung, colorectal, gastric, ovarian, and prostate." (PMID 33680922, 2020). "Together, these observations indicate that GRHL2 associates with epithelial traits across cancer types." (PMID 32676163, 2020). "GRHL2 negativebreast cancer is quite rare but is commonly associated with metastasis of thelymph nodes." (PMID 33173593, 2020). "GRHL2 has been implicated in cancer development and progression." (PMID 36768838, 2023). "In recent years, GRHL2 has been implicated in cancer progression." (PMID 26887977, 2016). "Given the known roles of GRHL2 in mitosis, and our observations that expression in GBM cells alters normal cell division, we hypothesized that a pan-cancer analysis of cells might indicate that GRHL2 expression associates with higher levels of aneuploidy in tumors." (PMID 37761927, 2023). "Most importantly, however, GRHL2 has emerged as a regulator of cancer cell proliferation, and an oncogenic potential has been attributed to GRHL2 when overexpressed in NIH3T3 cells." (PMID 40889682, 2025). "Our findings take account of distinct GRHL2 expression patterns reflecting different GRHL2 activation states but clearly need to be confirmed using distinct breast and other cancer cohorts." (PMID 40889682, 2025). "Our findings provide new insights into complex regulatory networks controlling GRHL2 activity in cancer cells." (PMID 40889682, 2025). "The formation of GRHL2 aggresome-like structures results in its functional inactivation, hence adding an additional layer of complexity to the regulation of the GRHL2 transcription factor in cancer cells." (PMID 40889682, 2025). "This strongly suggests that different cancer cohorts, methodology (e.g., GRHL2 mRNA versus protein analyses), or selection of distinct survival analysis endpoints severely affect the outcome of GRHL2 association analyses." (PMID 40889682, 2025). "In this study, we show that SUMO conjugation or deconjugation specifically mediated by SENP-1 and SENP-2 proteases represents a novel regulatory mechanism of GRHL2-dependent transcriptional activity in cancer cells." (PMID 40889682, 2025). "The transcription factor grainyhead-like 2 (GRHL2) plays a crucial role in a variety of human cancers." (PMID 40889682, 2025). "Despite its fundamental role in cancer development and progression, mechanisms modulating expression or activity of GRHL2 in cancer cells still remain elusive." (PMID 40889682, 2025). "Taken together, our results provide new insights into complex regulatory mechanisms governing GRHL2 activity in cancer cells." (PMID 40889682, 2025). "GRHL2 plays a crucial role in both normal developmental processes, particularly tubulogenesis, and cancer biology." (PMID 38429368, 2024). "These double-positive cells in the population characterize a cancer stem cell phenotype induced by elevated GRHL2." (PMID 39199676, 2024). "•PIK3CA and GATA3 were the main cancer driver genes in luminal samples, and candidate drivers were GRHL2 and SMURF2." (PMID 39208653, 2024). "In luminal samples, PIK3CA and GATA3 were the main cancer drivers, and other drivers were GRHL2 and SMURF2." (PMID 39208653, 2024).
cancer (continued). "Through the increase in CD44 and ALDH1 protein expression, GRHL2 stimulates the enrichment of cancer stem cells in the population." (PMID 39199676, 2024). "In keratinocytes and cancer cell lines, GRHL2 expression levels correlated with increased and decreased PCNA expression after overexpression and knockdown, respectively." (PMID 37745294, 2023). "Partitioning the data at this median value revealed a modest yet significant pan-cancer relationship between high GRHL2 expression and increased levels of aneuploidy." (PMID 37761927, 2023). "The transcription factor Grainyhead-like 2 (GRHL2) is a critical transcription factor for epithelial tissues that has been reported to promote cancer growth in some and suppress aspects of cancer progression in other studies." (PMID 36768838, 2023). "GRHL2 is located on chromosome 8q22.3, a genomic region that is frequently amplified or overexpressed in many cancers." (PMID 36768838, 2023). "In different cancer models, upregulation of GRHL2 expression has been directly correlated with lower EMT scores; whereas, cancers with mesenchymal features have reduced GRHL2 expression." (PMID 34868979, 2021). "The inflammatory infiltrate was more intense in poorly differentiated carcinomas and triple-negative carcinomas in which the expression of E-cadherin and GRHL2 was reduced, while EpCAM was overexpressed." (PMID 34680248, 2021). "Being a pivotal gatekeeper of epithelial integrity, GRHL2 suppresses EMT in a multipronged manner across cancer entities." (PMID 32974388, 2020). "Conversely, the amplitude of the epithelial TF GRHL2 was increased in samples from cancer patients compared with those derived from healthy controls." (PMID 31604930, 2019). "In epithelial and cancer cell lines, Grhl2 is required for maintenance of epithelial phenotype and regulation of EMT21,27." (PMID 31171776, 2019). "Previous studies demonstrated that GRHL2 knockdown resulted in a significant reduction in cell proliferation in various cancer cells." (PMID 28960866, 2017). "With its expression negatively correlated with the EMT score, GRHL2 serves as an epithelial signature in cancers." (PMID 26887977, 2016). "In this study, we scrutinized the expression of GRHL2, within and across different cancer types, in relation to the EMT score." (PMID 26887977, 2016). "Observing that Grhl2-overexpression leads to increased metastatic potential in vitro, we established a model assuming Grhl2-induced or -inhibited genes confer poor or favorable prognosis respectively for cancer metastasis." (PMID 23441166, 2013). "Multiple functional assays confirm that Grhl2 plays a dominant role in maintaining the epithelial phenotype, and changing Grhl2 levels in cancer cells leads to EMT/MET induction." (PMID 23284647, 2012). "Although the combined activation of transforming growth factor β/WNT signaling pathways has been demonstrated to induce ZEB1-dependent repression of GRHL2 expression and EMT, surprisingly little is known about mechanisms and signaling pathways regulating GRHL2 activity in cancer cells." (PMID 40889682, 2025). "Notably, GRHL2 has previously been implicated as both inhibitor and activator of EMT in various cancer cell lines, and this activity appears to be context-dependent." (PMID 39199676, 2024). "GRHL2 is located on chromosome 8q22 that is frequently amplified in carcinomas." (PMID 38706844, 2024). "GRHL2 plays a critical role in oriented cell division and the positioning of the mitotic spindle, and its expression in epithelial cells likely represents a barrier to epithelial-to-mesenchymal transition in cancer." (PMID 37761927, 2023). "In contrast, GRHL2 is located on chromosome 8q22 which is frequently amplified or overexpressed in many cancers and hence may rather have an oncogenic function." (PMID 36768838, 2023).